MITF (melanocyte inducing transcription factor)
Diseases named in the same sentence as MITF in open-access papers (continued):
Sharing a sentence is not in itself a finding about the gene and the disease.
melanoma (continued). "A zebrafish model that mimics human resistant-melanoma subtypes exhibiting low MITF showed an upregulation of genes involved in stemness and invasiveness." (PMID 35631574, 2022). "CH5552074 and CH6869398 are two MITF protein suppressors that have shown in vivo efficacy in melanoma xenograft models." (PMID 35954441, 2022). "A panel of biochemical assays and RNA-sequencing revealed that MITF was responsible for the protective influence of Wnt/β-catenin signaling on melanoma cell ferroptosis, with downstream effectors PGC1α and SCD1 greatly implicated." (PMID 36429010, 2022). "To trace melanoma cells through disease states, we first set out to establish an inducible cre/loxP system on the MITF-dependent melanoma background." (PMID 35929478, 2022). "Whereas down-regulation of p14ARF results in sustained activity of dysfunctional mitochondria with higher metabolic plasticity.Melanoma exhibits increased mitochondrial respiration, mainly related to MITF expression." (PMID 36620597, 2022). "In melanoma, MITF repression sensitizes melanoma cells to ROS levels through the direct regulation of genes involved in the response to oxidative stress." (PMID 35912100, 2022). "In conclusion, we generated SOX10KO clones using CRISPR/Cas9 in an MITF-methylated melanoma background." (PMID 36040798, 2022). "MITF-AXL axis is key during melanoma development, and can easily condition the fate of targeted therapies." (PMID 35054460, 2022). "Of note, MITF is a key regulator of phenotypic identity and melanoma cell fate, able to promote differentiation and proliferation." (PMID 35912100, 2022). "USP13 can regulate microphthalmia-associated transcription factor (MITF), an essential modulator of melanoma growth." (PMID 35173307, 2022). "In the invasive MITF-low state PGC1α depletion rewires melanoma cells towards metabolic dependency on HIF1α-mediated glycolysis and glutamine usage." (PMID 35912100, 2022). "The hot water extract of Pleurochrysis carterae inhibited melanin synthesis by downregulating the tyrosinase and MITF levels in B16F1 melanoma cells." (PMID 35883808, 2022). "Due to the fact that inhibition of MITF decreases cell growth in melanoma, this protein is worth examining as a target molecule for the TNBC therapy." (PMID 36045272, 2022). "To control for this, we examined the publicly available melanoma/skin Cancer Cell Line Encyclopedia gene expression data to obtain 2248 upregulated and 2799 downregulate genes in 13 high MITF vs 13 low MITF‐expressing cell lines." (PMID 35771179, 2022). "MITF is also the transcriptional regulator of v-ATPase gene expression in melanocytes and melanomas." (PMID 35563798, 2022). "This is the only study that implicates USP13 deubiquitinase in melanoma development by regulating MITF protein stability." (PMID 35884430, 2022). "In melanoma, the regulatory activity of YAP is able to regulate the phenotype differentiation of melanoma cells through YAP/PAX3/MITF or YAP/TEAD/SMAD transcription in sensing the stiffness of the ECM." (PMID 36233186, 2022). "MITF, a melanocytic lineage-specific transcription factor, has been certified as a master regulator of melanocyte homeostasis and melanoma progression." (PMID 36268034, 2022). "High-level focal amplification of MITF has been found to mediate BRAF inhibitor resistance in melanoma." (PMID 35580987, 2022). "Transcriptional reprogramming is a critical determinant of the phenotype switch of melanoma cells and is controlled by distinct transcriptional master-regulators, such as MITF, a crucial regulator of the melanoma phenotypic states." (PMID 35159386, 2022). "Taken together, BRN2 is suggested as a critical regulator that is involved in drug resistance and invasion during melanoma treatment as a counterbalance to the MITF." (PMID 36224606, 2022). "Lastly, immunostained sections from syngeneic melanomas after Cpd1 treatment confirmed enriched MITF protein expression in vivo (upper row)." (PMID 35650266, 2022).
melanoma (continued). "Transient MGRN1 depletion or permanent knockdown in human melanoma cells led to a differentiated phenotype by an apparently MITF-independent mechanism." (PMID 35892921, 2022). "In these ways, the presence or absence of TFAP2 paralogs mediates a phenotypic switch between cell proliferation and cell-cell adhesion in a cell line model of melanoma, in part through their interactions with MITF." (PMID 35580127, 2022). "The role of MITF is well-known in melanoma, and recent studies suggest that MITF overexpression in kidney angiomyolipoma cells and clear cell renal cell carcinoma (ccRCC) improve cell growth, proliferation, and invasion in vitro and in vivo." (PMID 36551682, 2022). "MITF is an established contributor of melanoma heterogeneity through its multi-pathway influence on melanocyte differentiation, proliferation, and metastatic potential." (PMID 36292642, 2022). "All epigenetic drugs had a predominant inhibitory effect on the expression of the melanoma differentiation-related proteins MITF and SOX-10 and of the transcription factor MYC." (PMID 36397155, 2022). "USP13 has been identified as a deubiquitination enzyme of MITF to modulate the ubiquitination level of MITF, affecting the survival of melanoma cells." (PMID 35445009, 2022). "Beyond MITF, other melanoma lineage-restricted factors, involved in coordinating metabolism and cell fate have been described." (PMID 35912100, 2022). "In particular, low MITF in melanoma was shown to induce phenotype switching as an invasive mechanism, and thus the changing expression of this transcription factor can lead to the subsequent generation of resistant melanoma subpopulations." (PMID 36292642, 2022). "In particular, PGC1α and SCD1 were proved as two main effectors downstream of the Wnt/β-catenin-MITF pathway in melanoma cell ferroptosis." (PMID 36429010, 2022). "Given the importance of the MITF gene in the melanocytic lineage, we examined the MITF pathway in two BRAFV600E melanoma cell lines treated with the same conditions as in the RNA-seq experiment." (PMID 35580987, 2022). "Of particular relevance is the involvement of the transcription factor MITF, which can control melanoma cell fate, at least in part as a crucial and increasingly recognized regulator of metabolism." (PMID 35912100, 2022). "In line with “MITF-low” and “proliferative” GESs, melanoma cells with “EMT” GES had the lowest level of MITF expression." (PMID 35884783, 2022). "All melanomas exhibit at least two distinct MITF transcriptional cell states, which are represented by melanomas with high levels of MITF, versus melanomas with low levels of MITF." (PMID 36248850, 2022). "In accordance with this, MITF expression was recently shown to be reduced in approximately 50% of relapsed melanoma cases." (PMID 36040798, 2022). "Distinct downstream target genes are responsible for the versatile functions of MITF in different aspects of melanocyte and melanoma biology, including DNA damage repair, cell metabolism, cell differentiation, invasion and metastasis." (PMID 36429010, 2022). "Given that an MITF-low is a deadly status for melanoma, an interesting possibility for therapy would be to effectively covert them to MITF-high by manipulating pioneer factors such as TFAP2 paralogs or other MITF-cofactors." (PMID 35580127, 2022). "Of note, the master regulator of mitochondrial function and antioxidant system, PGC1α, is the main transcriptional target of MITF and regulates mitochondrial biogenesis to promote tumor growth in melanoma." (PMID 36429010, 2022). "This trend is in accordance with experimental evidence that suggests that OXPHOS in melanoma cells is regulated by PGC1α, a downstream target of MITF, a key regulator of melanocyte differentiation." (PMID 36003764, 2022).
melanoma (continued). "SOX10 is, like MITF, heterogeneously expressed in melanoma, and has been proposed as a regulator of phenotype switching in cutaneous melanoma since its genetic ablation impairs proliferation and promotes the acquisition of invasive features and drug tolerance." (PMID 35912100, 2022). "Subsequent mechanistic studies revealed that MITF mediated the effect of Wnt/β-catenin signaling on melanoma cell ferroptosis, and PGC1α and SCD1 were documented as two main effectors downstream of Wnt/β-catenin-MITF pathway." (PMID 36429010, 2022). "Reduced expression of MITF during the development of resistance was also observed in the majority of melanoma cell populations derived from patients." (PMID 35565444, 2022). "Since MITF directly regulates transcription of ADAM10, high levels of MITF within melanoma cells lead to an upregulation of this sheddase and a reduction of NK-cell recognition of the tumor." (PMID 36551603, 2022). "To further explore the differences observed between in vitro and in vivo findings, we used CRISPR/Cas9 to deplete SOX10 in an MITF-methylated melanoma cell background." (PMID 36040798, 2022). "The rheostat model proposed by the group of Goding provides explanation to the apparent paradox that MITF controls or represses the proliferation or the motile ability of melanoma cells." (PMID 35682684, 2022). "Expressed in about 80% of human melanoma, MITF displays a central regulatory role in melanoma cell phenotypic plasticity." (PMID 35091687, 2022). "MITF high and MITF low melanoma cells can coexist in a UM and contribute to intra-tumoural heterogeneity, as has recently been described." (PMID 35682684, 2022). "This was reflected by the overexpression of the melanocyte-specific transcription factor MITF (log2fold change = 2.2, adjusted p-value = 1.0 × 10−5), which is known to control the proliferation, migration, and invasion of melanoma cells in CMs." (PMID 35053440, 2022). "Apart from melanoma, studies have connected MITF with a role in multiple cancers, including non-small cell lung cancer, pancreatic cancer and hepatocellular carcinoma." (PMID 35159049, 2022). "In line with its central role, MITF is finely regulated to ensure the homeostasis of melanocytes or melanoma cells." (PMID 35091687, 2022). "At this stage of research, it is difficult to clearly state the role of MITF in the anti-melanoma action of tested tetracyclines." (PMID 35055021, 2022). "Our results indicate that loss of MITF reduces the shedding of the NKG2D ligands and enhances NK cell-mediated killing of melanoma cells." (PMID 33789714, 2021). "Using siRNA-mediated MITF knockdown in three human melanoma cell lines expressing high levels of MITF (501mel, SK28, HBL) led to a significant increase of PTEN protein and mRNA levels." (PMID 34140478, 2021). "Collectively, these results support that both melanocytes and MITFhigh/AXLlow melanoma cells have high pigmentation activity, concordant with high MITF expression." (PMID 37849907, 2021). "In melanomas, MITF can behave as an oncogene, and in approximately 20% of melanomas, it amplifies and promotes the proliferation of tumor cells." (PMID 34571969, 2021). "TNFα effects were reversible in both melanocytic (SKMel28, MP46, MEL270, OMM1) and dedifferentiated (HT144, MM200) melanoma cell lines, with the partial to complete restoration of MITF and Melan A expression after TNFα removal." (PMID 34073253, 2021). "Results of this research show that the miRNA-183 cluster targets the 3′-UTR of MITF in B16 mouse melanoma cells." (PMID 34198907, 2021). "In conclusion, our work establishes the role of MITF as a regulator of the ubiquitination pathway, in melanoma cells, through transcriptional regulation of several genes, among which FBXO32." (PMID 33462405, 2021). "In melanoma cell lines MITF amplification is commonly accompanied by CDKN2A inactivation and BRAF mutation." (PMID 33556121, 2021).
melanoma (continued). "Consistent with previous reports, the melanoma cells with high MITF expression levels exhibit low AXL Receptor Tyrosine Kinase (AXL) expression." (PMID 37849907, 2021). "In the present study, PA significantly suppressed the expression of MITF in α-MSH-induced melanoma cells." (PMID 33917915, 2021). "This large pleiotropism indicates that MITF impacts and coordinates numerous key molecular pathways, to regulate melanocytes and melanoma homeostasis." (PMID 33462405, 2021). "It is worth mentioning that an increase in the number of focal adhesions was restricted to SkMel28 melanoma cells in which MITF protein level was reduced upon vemurafenib treatment." (PMID 33438577, 2021). "MITF plays a central role in mediating intratumoral heterogeneity, plasticity, and phenotype switching in melanoma." (PMID 34071193, 2021). "We identified that HuR regulates the microphthalmia-associated transcription factor (MITF) that has been implicated in both intrinsic and acquired drug resistance in melanoma and is a putative therapeutic target in melanoma." (PMID 33418925, 2021). "The second-largest network hub, by number of microRNA–mRNA associations (266/1739, 15%), comprised two microRNAs which were previously found to be differentially enriched in the ‘MITF-low’ cluster of the TCGA melanoma samples: miR-100-5p and 125b-5p." (PMID 34771465, 2021). "Our findings reveal a new role for MITF in regulating the expression of genes that are essential for creating the melanoma microenvironment, establishing a link to melanoma progression and drug resistance." (PMID 33438577, 2021). "In line with this, gene expression of MITF target genes seemed to correlate with poorer survival in melanoma patients with high-collagen tumors." (PMID 34071193, 2021). "Some of the most important signaling pathways involved in the pathogenesis of melanoma include the MAPK, PI3K/PTEN/AKT, and microphthalmia-associated transcription factor (MITF) signaling pathways." (PMID 34064863, 2021). "We evaluated the expression of PGC1α also because its transcription in melanoma cells is activated by MITF, which is strongly downregulated in A375 AC-null cells." (PMID 33806766, 2021). "MNK1/2 inhibitors, which block eIF4E phosphorylation, decreased melanoma cell invasion, restored MITF expression and repressed NGFR expression in BRAFi-resistant cells, and cooperatively inhibited their growth in combination with vemurafenib." (PMID 34604096, 2021). "In this work, we sought to investigate the role of MITF in the ubiquitination processes in melanoma cells." (PMID 33462405, 2021). "When we increased MITF levels in UACC-62 melanoma cells with a doxycycline-inducible expression vector, TGFA was repressed on RNA level, and TGFα secretion, measured by ELISA, was clearly reduced." (PMID 33916908, 2021). "Upon MITF loss, an EMT-like process has been described to be involved in driving drug resistance in melanoma." (PMID 33438577, 2021). "ATF4 has been shown to negatively regulate the CRE of the Melanocyte Inducing Transcription Factor (MITF) promoter upon glucose deprivation in melanoma." (PMID 33418948, 2021). "Different from the paradoxical role of MITF in cell proliferation, many reports have provided compelling evidence to support the essential role of MITF in melanoma cell survival." (PMID 34924562, 2021). "Due to the specific expression of MITF in the melanocytic lineage, this indirect MITF-dependent effect of NRF2 is typical for melanoma but cannot occur in other cancer or tissue types." (PMID 33916908, 2021).
melanoma (continued). "Recent evidence points to a relationship between MITF expression and autophagy induction in melanoma cells." (PMID 33806766, 2021). "We conclude that individuals with functional damage to the MITF protein have substantially higher rates of melanoma." (PMID 34290314, 2021). "Low expression or loss of MITF was also shown to increase glycosaminoglycan metabolism, ECM organization and structural organization in melanoma cells." (PMID 35127523, 2021). "Microphthalmia-associated transcription factor (MITF), the key transcription factor in melanocytes, is also known to play a crucial role in melanoma phenotypic switch and therapy resistance." (PMID 33462405, 2021). "The equivalent GSEA of mRNAs inversely correlated with the ‘MITF-low’ microRNA network in cell lines shared 2/10 enriched gene sets with the TCGA melanoma ‘MITF-low’ network, including estrogen early response and adipogenesis." (PMID 34771465, 2021). "The majority of melanoma cell lines (23/40: 15/31 cutaneous, 8/9 uveal) showed features of the melanocytic state, including the high expression of MITF and Melan A along with low levels of AXL and/or NGFR." (PMID 34073253, 2021). "The heterogeneity of melanoma having cells in both MITF high and low states and their ability to transition from one state to another is thought to confer drug resistance." (PMID 35008286, 2021). "Zebrafish embryo-based platforms have shown that the small molecule, SKLB226, can downregulate MITF mRNA, prevent zebrafish pigment cell migration and had similar effects on MITF and migration in mammalian melanoma cell culture." (PMID 34067095, 2021). "Since its discovery, MiTF has been shown to be a prominent key regulator of many aspects of melanocyte and melanoma biology." (PMID 33441180, 2021). "Switching between various phenotypes, e.g., high MITF (less invasive and proliferating) and low MITF (slowly proliferating but invasive, giving rise to metastatic cells) is typical for melanoma." (PMID 34063141, 2021). "Type 1 (N1/M1) lesions are characterized by pigmentation-type and MITF gene signatures and prevalent NRAS mutations in M1 melanomas." (PMID 34281234, 2021). "Another interaction of MITF with the cell is suggested by the suppression of melanoma colony formation by MITF downregulation, which can be rescued by CDK2 overexpression." (PMID 34698095, 2021). "Very recently, our group identified FBXO32, a key component of the SCF ubiquitin- protein ligase complexes, as a MITF target, regulating melanoma cell migration and proliferation." (PMID 33800394, 2021). "In fact, MITF has been proposed to act as a rheostat where the levels of MITF activity determine the phenotypic state of melanoma cells." (PMID 33438577, 2021). "On the other hand, increased MITF expression decreased the invasiveness of melanoma cells by reducing DIA1 expression, which controls actin polymerization and is therefore involved in cytoskeletal reorganization." (PMID 34071193, 2021). "We used network analysis to define two core microRNA–mRNA networks in melanoma tissues and cell lines corresponding to ‘MITF-low’ and ‘Keratin’ transcriptomic subsets of melanoma." (PMID 34771465, 2021). "In particular, a clear mechanistic overview of the different signaling pathways involved upstream of MITF—the key player in melanoma—would be of utmost importance." (PMID 34356645, 2021).